DNMT1 (DNA methyltransferase 1)
Diseases named in the same sentence as DNMT1 in open-access papers (continued):
Sharing a sentence is not in itself a finding about the gene and the disease.
dilated cardiomyopathy (1 paper, 2021). Cardiomyopathy which is characterized by dilation and contractile dysfunction of the left and right ventricles. "Following DNMT1 siRNA treatment, the genes were most up‐regulated in the pathways related to formation of contractile fiber, heart development, and hypertrophy or dilated cardiomyopathy." (PMID 34235895, 2021).
endometrial tumors (1 paper, 2014). "Previously, miR-152 was demonstrated to target DNMT1 expression in endometrial tumors." (PMID 25004396, 2014).
Erythema (1 paper, 2024). Redness of the skin, caused by hyperemia of the capillaries in the lower layers of the skin. "Associated with facial erythema, joint pain, anti-dsDNA antibody and anti-IgG antibody.Targeting DNMT1 to inhibit MyD88 methylation and promoting TLR-mediated cellular inflammatory responses." (PMID 39835138, 2024).
gastric adenocarcinoma (1 paper, 2022). "This study's results indicate the correlation between DNMT1 gene֝ expression in gastric antral epithelial cells and some gastric adenocarcinoma risk factors, including aging and H. pylori genotypes infection, which is consistent with the results of previous studies." (PMID 36147796, 2022). "According to the results of previous studies, the DNMT1 gene's expression in gastric epithelial cells increases with age increasing, gastric adenocarcinoma, and H. pylori cagA genotype infection." (PMID 36147796, 2022). "In gastric antral epithelial cells of both groups of patients with H. pylori infection and gastric adenocarcinoma, the DNMT1 gene expression was significantly increased." (PMID 36147796, 2022). "However, they showed the increased DNMT1 gene expression was not correlated with the prognosis and clinicopathological including gastric adenocarcinoma area and grade tumor consonant with the present study." (PMID 36147796, 2022).
gastric atrophy (1 paper, 2012). "In addition, our results revealed that C allele at rs8111085 and G allele at rs10420321 in the DNMT1 gene protect the carrier against H. pylori infection, while, surprisingly, they are associated with increased risks in developing gastric atrophy." (PMID 23049933, 2012). "Our results suggested that SNPs of DNMT1 could be used as genotypic markers for predicting genetic susceptibilities to H. pylori infection and risks in gastric atrophy." (PMID 23049933, 2012). "Further studies of DNMT1 sequence variants and their biologic functions may shed light on associations of the DNMT1 polymorphism and the risk for H. pylori infection and for gastric atrophy." (PMID 23049933, 2012). "In addition, polymorphisms of the DNMT1 gene are also significantly associated with increased risks of developing gastric atrophy, suggesting that they could be used as biomarkers for predicting genetic susceptibilities to H. pylori infection and risk assessments in gastric atrophy." (PMID 23049933, 2012).
gastric disease (1 paper, 2017). "We could speculate from the results above that with the increase of the severity of the gastric disease, DNMT1 protein expression increased at the same time." (PMID 29221215, 2017).
glomerulonephritis (1 paper, 2022). A renal disorder characterized by damage in the glomeruli. "To analyze whether HBx affects DNMT1 expression in HBV-associated glomerulonephritis, we generated stable HBx-overexpressing cells, HBx-HK-2 cell lines, and HBx-podocytes." (PMID 35765066, 2022).
goiter (1 paper, 2019). Enlargement of the thyroid gland usually caused by lack of iodine in the diet, hyperthyroidism, or thyroid nodules. "In this research, we determined the promoter methylation status of four tumor suppressor genes (SLC5A8, RASSF1, MGMT, and DNMT1) and compared the results of 55 PTC cases with 40 goiter patients." (PMID 31754358, 2019). "However, our results indicated that DNMT1 methylation in PTC patients, in comparison with goiter patients (controls), was less than SLC5A8, RASSF1, and MGMT." (PMID 31754358, 2019).
Granuloma (1 paper, 2020). A compact, organized collection of mature mononuclear phagocytes, which may be but is not necessarily accompanied by accessory features such as necrosis. "TET3 correlated positively with TET2, DNMT1, and negatively correlated with granulomas number and miR31-3p and 122-3p expression." (PMID 32078636, 2020). "Liver damage induced downregulation of DNMT1 and TET3 expression considering granulomas number." (PMID 32078636, 2020). "Correlation analysis among the expression of TET1, 2 and 3 and DNMT1, 3A and 3B indicated that there was a negative correlation between DNMT1 and TET3 gene expression and granuloma number in EBi3-/-I." (PMID 32078636, 2020). "In this work it was observed that there is a negative correlation between this miRNA and the DNA methyltransferase and demethylase genes (DNMT1 and TET3) and positive with the number of granulomas found in the liver of EBi3-/-I mice, which does not occur in WTI." (PMID 32078636, 2020).
hearing disorder (1 paper, 2018). A disorder characterized by the partial or complete loss of the ability to detect sounds due to damage to the ear structures or inability of the brain to properly interpret or process the auditory signals it receives from the anatomic structures of the ear. "However, considering the vital roles of DNMT1 in hearing disorders and of DNMT3A in oxidative stress, we speculated that polymorphisms in DNMT1, DNMT3A and their interactions could be associated with genetic susceptibility to NIHL." (PMID 30111769, 2018).
hemoglobinopathies (1 paper, 2021). "In addition, recent work identified a DNMT1 germline missense mutation giving rise to HPFH, thus providing direct evidence for DNMT1 as a key γ-globin epigenetic co-repressor and further validating it as a therapeutic target for hemoglobinopathies." (PMID 34713248, 2021).
hepatic (1 paper, 2021). "Collectively, both in vitro and in vivo data imply a direct regulation of DNMT1 on ND6 methylation and transcription, which plays vital role in mitochondrial dysfunction associated hepatic IR." (PMID 34141522, 2021).
hepatic diseases (1 paper, 2023). "Thus, glycyrrhizin used for the treatment of hepatic diseases and itching dermatitis was shown to possess an anti-fibrotic effect in SSc dermal and lung fibroblasts via downregulation of Dnmt1, upregulation of Fli1, and induction of MMP1 gene expression via an ERK1/2-dependent mechanism." (PMID 36768203, 2023).
histiocytic lymphoma (1 paper, 2023). "In addition, to find out whether knockdown of UHRF1 or DNMT1 also enhances differentiation in other cell line, we used another blood cancer cell line U-937, which is obtained from histiocytic lymphoma." (PMID 37573395, 2023).
Hyperinsulinemia (1 paper, 2018). An increased concentration of insulin in the blood. "Indeed, hyperinsulinemia increased the expression of Nox-2 and Dnmt1 in human HSCs." (PMID 29295997, 2018). "Hyperinsulinemia also increased the expression of NOX-2 and DNMT1 in human HSCs." (PMID 29295997, 2018).
hyperthyroidism (1 paper, 2019). Overactivity of the thyroid gland resulting in overproduction of thyroid hormone and increased metabolic rate. "Newly diagnosed hyperthyroid patients had genome-wide hypomethylation and lower DNMT1 expression in T and B lymphocytes; while relief of hyperthyroidism with antithyroid drugs restored the global DNA methylation and DNMT1 expression." (PMID 31555215, 2019).
hypoadiponectinemia (1 paper, 2015). "In db/db mice, hypoadiponectinemia was ameliorated by the inhibition of DNMT1 activity by RG108 through reducing DNA hypermethylation at the R2, consequently alleviating metabolic dysregulation." (PMID 26139044, 2015).
intrahepatic cholangiocarcinoma (1 paper, 2021). A carcinoma that arises from the intrahepatic bile duct epithelium in any site of the intrahepatic biliary tree. "HCV infection also decreases miR-124 level via Dnmt1, resulting in cell migration and invasion in intrahepatic cholangiocarcinoma (ICC) cells." (PMID 34336665, 2021).
intrauterine growth restriction (1 paper, 2020). "In postnatal piglets with spontaneous intrauterine growth restriction, the expression of DNMT1 in the ileum was reported to be reduced." (PMID 32251454, 2020).
invasive breast carcinoma (1 paper, 2022). A carcinoma that infiltrates the breast parenchyma. "Furthermore, DNMT1, histone H1, HP1 and SUV39H1 were downregulated in invasive breast cancers (IBCs) with PIWIL2 underexpression, while DNMT1 was downregulated only in IBCs with PIWIL4 underexpression." (PMID 35637965, 2022).
Kaposi's sarcoma (1 paper, 2021). A malignant neoplasm characterized by a vascular proliferation which usually contains blunt endothelial cells. "DNMT1 and DNMT3B are involved in Kaposi’s sarcoma, and DNMTs are upregulated in leiomyosarcoma." (PMID 35008848, 2021).
keloid (1 paper, 2020). An irregularly shaped, elevated mark on the skin caused by deposits of excessive amounts of collagen during wound healing. "Fibroblasts from scars and keloids express high levels of DNA methyltransferase 1 (DNMT1) compared to normal skin fibroblasts." (PMID 32046094, 2020).
kidney damage (1 paper, 2023). "Additionally, the upregulation of DNMT1 can decrease cellular tolerance to oxidative stress by methylating and inhibiting the expression of antioxidant genes, thereby aggravating kidney damage." (PMID 37861555, 2023).
knee osteoarthritis (1 paper, 2022). "A matched case-control study showed that DNMT1, DNMT3A, and DNMT3B gene polymorphisms are significantly associated with radioactive primary knee osteoarthritis." (PMID 35747513, 2022).
latent infection (1 paper, 2016). "Thus, this enabled us to postulate that genipin might promote the KSHV latent infection by activating DNMT1 and inducing aberrant DNA methylation." (PMID 27736870, 2016).
liver dysfunction (1 paper, 2012). "The purpose of this study was to determine whether chronic alcohol feeding modulates the expression/activity of DNA methylation machinery and whether reduced expression of Dnmt1 has any effect on alcohol-induced liver dysfunction." (PMID 22905112, 2012).
malignant meningiomas (1 paper, 2013). "DNMT1 has been previously shown to interact with PRC component EZH2 and to methylate PRC targeted genomic regions, therefore increased DNMT1 levels in malignant meningiomas may be recruited to PRC-targeted CpG islands and induce focal DNA hypermethylation." (PMID 23349797, 2013).
malignant salivary gland tumors (1 paper, 2021). "On the other hand, some studies have found that DNMT1 expression was similar among normal salivary gland tissue and benign and malignant salivary gland tumors." (PMID 35048062, 2021).
melasma (1 paper, 2019). "The greater expression and activity of DNMT1 found in melasma lesions than in unaffected skin is probably related to solar exposure." (PMID 31143777, 2019). "We observed that DNMT3 and DNMT1 are increased in melasma and downregulated by the use of sunscreen in combination with 0.05% retinoic acid, 4% niacinamide, or placebo." (PMID 31143777, 2019). "At the end of treatment, all three groups showed improvement in melasma and reduction in DNMT1 and DNMT3b." (PMID 31143777, 2019). "After eight weeks of treatment, a significant decrease of DNMT1 was observed in melasma lesions in all groups (ANOVA, p = 0.02)." (PMID 31143777, 2019).
microcephaly (1 paper, 2008). A congenital or acquired developmental disorder in which the circumference of the head is smaller than normal for the person's age and sex. "Dnmt1−/− mice die early in gestation, but knock-down approaches have revealed that reduction of Dnmt1 leads to microcephaly (small heads) and defects in terminal differentiation in some organs." (PMID 17931718, 2008).
monocytic leukemia (1 paper, 2019). "In established HMA-resistant cell lines from a human monocytic leukemia cell line (MOLM-13), protein levels of DNMT3B were found upregulated compared to parental cell line and mRNA expression of DNMT1 and DNMT3A in HMA-resistant cell lines decreased compared to parental cell line." (PMID 31331399, 2019).
mucinous carcinomas (1 paper, 2023). "Like serous carcinomas, mucinous carcinomas also displayed a higher expression of DNMT1 and DNMT3L in comparison with non-neoplastic tissues (p = 0.042 and p = 0.045, respectively)." (PMID 37894317, 2023).
muscular dystrophy (1 paper, 2016). Muscular dystrophy (MD) refers to a group of more than 30 genetic diseases characterized by progressive weakness and degeneration of the skeletal muscles that control movement. "It provides a new direction for the study of myogenesis and will be interesting in future studies to determine whether Dnmt1 loss translates to premature aging of the tissue or muscular dystrophy." (PMID 27752090, 2016).
Nijmegen breakage syndrome (1 paper, 2018). Nijmegen breakage syndrome is a rare genetic disease presenting at birth with microcephaly, dysmorphic facial features, becoming more noticeable with age, growth delay, and later-onset complications such as malignancies and infections.
oral candidiasis (1 paper, 2023). Infection of the mucosal lining of the mouth with the fungus Candida albicans. "We noticed that the “AKT signaling” (R-HSA-1257604) pathway is enriched in the DNMT1 core module, and it is worthwhile to mention that AKT signaling is crucial for T-cell differentiation and it encourages naive CD4 T cells to differentiate into Th17 to prevent oral candidiasis." (PMID 37900175, 2023).
oral lichen planus (1 paper, 2021). Oral lichen planus is a chronic inflammatory oral condition of unknown aetiology characterized by T-cell-mediated chronic immune response and abnormal epithelial keratinization cycle. "For example, DNMT3A and DNMT3B are increased in lip and oral carcinogenesis, and high levels of DNMT1 can also be seen in oral lichen planus." (PMID 35048062, 2021).
ovarian endometriosis (1 paper, 2024). A non-neoplastic disorder characterized by the growth of endometrial tissue in the ovaries. "Further, estrogen influences epigenetic processes by regulating the DNA methyltransferase 1 (DNMT1)-dependent hypermethylation of the runt-related transcription factor 3 (RUNX3) in the malignant transformation of ovarian endometriosis." (PMID 38673891, 2024).
overnutrition (1 paper, 2021). An imbalanced nutritional status resulting from excessive intake of nutrients. "A significant effect of maternal overnutrition was evident for DNMT1 and DNMT3B expression in the AC of day-28 conceptuses." (PMID 34573470, 2021).
pancreatic endocrine tumors (1 paper, 2016). "Immunofluorescence (IF) and western blot assays were used to identify increased DNMT1 protein levels in MEN1-parathyroid tumors, mouse pancreatic endocrine tumors from Men1 KO mice, and mouse parathyroid tumors from a different Men1 KO mouse model." (PMID 26871472, 2016).
Pancytopenia (1 paper, 2023). An abnormal reduction in numbers of all blood cell types (red blood cells, white blood cells, and platelets). "Dnmt1 deletion in murine HSCs results in rapid death from profound pancytopenia due to absence of all HSCs and progenitors, while low-level Dnmt1 expression results in a marked decrease of lymphoid progenitors and decreased self-renewal capacity in serial transplantation experiments." (PMID 37325668, 2023).
papillary thyroid carcinoma (1 paper, 2026). "In papillary thyroid carcinoma, DNA hypermethylation mediated by DNA methyltransferase 1 (DNMT1) in the promoter region of METTL16 leads to reduced transcription and expression of METTL16." (PMID 41459114, 2026).
papilloma (1 paper, 2010). A benign epithelial neoplasm that projects above the surrounding epithelial surface and consists of villous or arborescent outgrowths of fibrovascular stroma. "Intriguingly moreover, the status of the histone 3 Lys 9 methylation (H3K9me), but not the CpG methylation around the p16INK4a gene promoter, was well correlated with the levels of DNMT1 expression during the course of papilloma development." (PMID 20157424, 2010). "Interestingly, the levels of DNMT1, which is known to repress p16INK4a gene expression, were significantly increased in early-stage papilloma and subsequently reduced in late-stage papillomas." (PMID 20157424, 2010). "Our results strongly suggest that the DNA damage response (DDR) triggered by hyper-cell proliferation plays critical role(s) in blocking DNMT1 gene expression, at least partly, through the elevation of the reactive oxygen species (ROS) level in late-stage papillomas." (PMID 20157424, 2010). "However, it was unclear how DNMT1 is reduced in the late stage of papilloma development." (PMID 20157424, 2010).
peripheral nerve injury (1 paper, 2023). Injury to a peripheral nerve. "DNMT1, with an established role in canonical methylation activity but also with recognized de novo methylation actions, and DNMT3a, through repression of Kcna2, were found upregulated in the DRG after peripheral nerve injury in mice, and their inhibition or knockout diminished pain hypersensitivity." (PMID 37108466, 2023).
pituitary tumor (1 paper, 2019). A benign or malignant neoplasm affecting the pituitary gland. "DNMT1 and DNMT3A overexpression has been detected in pituitary tumors." (PMID 31139150, 2019).
PN tumors (1 paper, 2021). "Furthermore, based on the N-Myc ChIP-seq data, we found that N-Myc binding was enhanced at the promoters of Dnmt1, Dnmt3b, and Mdb4 in PRN (primarily poorly differentiated histology) compared to PN tumors (primarily adenocarcinoma histology)." (PMID 34099734, 2021).
recurrent disease (1 paper, 2025). "In this study, the associations between methylation markers (DNMT1, DNMT3A, and DNMT3B) and both locoregional recurrent disease and disease-specific mortality in patients with locally advanced LSCC treated with definitive, curatively intended radiotherapy alone was investigated." (PMID 40507223, 2025).
Rett syndrome (1 paper, 2025). A severe neurodevelopmental disorder affecting the central nervous system.
Right ventricular hypertrophy (1 paper, 2019). In this case the right ventricle is more muscular than normal, causing a characteristic boot-shaped (coeur-en-sabot) appearance as seen on anterior- posterior chest x-rays. "Histological changes (right ventricular hypertrophy index, medial wall thickness in pulmonary arteries (PAs)) and DNMT1 protein levels in rat PAs or primary human PA smooth muscle cells (HPASMCs) exposed to cigarette smoke extract were assessed." (PMID 30845941, 2019).
serous ovarian carcinoma (1 paper, 2022). "Then, we analyzed if DNMT1, 3A, 3B1, and DNMT3B3, 3B4, 3B5, 3B6, 3B7, and 3B3Δ5 isoforms’ expression was associated with the stage of disease and tumor grade in serous ovarian carcinoma (SOC)." (PMID 36361550, 2022).
small cell carcinoma (1 paper, 2015). A neuroendocrine carcinoma composed of small malignant cells which are often said to resemble "oat cells" under the microscope. "miR-148b reverses cisplatin-resistance in non-small cell cancer cells via negatively regulating DNMT1 expression." (PMID 25927928, 2015).
spina bifida (1 paper, 2022). A congenital neural tube defect in which vertebrae are not fully formed. "From the in vitro experimentations, differential DNMT1 RNA expressions were found between spina bifida affected newborns and their respective mothers when compared with controls." (PMID 36394275, 2022).